SNORD109A (small nucleolar RNA, C/D box 109A)
Synonyms: HBII-438a
Gene: Small nucleolar RNA gene on chromosome 15 (25,041,974 to 25,042,040, forward strand). Ensembl gene ENSG00000274640.
Gene Ontology:
Biological process: RNA processing
Cellular component: nucleolus
Homologues: Orthologues: macaque SNORD109A (100% identical). Paralogues in human: SNORD109B (100% identical).